HOTTIP (HOXA distal transcript antisense RNA)
Synonyms: HOXA-AS6; RP1-170O19.3; HOXA13-AS1; formerly NCRNA00213
Gene: Long non-coding RNA gene on chromosome 7 (27,198,575 to 27,207,259, forward strand). Ensembl gene ENSG00000243766.
Diseases named in the same sentence as HOTTIP in open-access papers:
HOTTIP is named in the same sentence as 87 diseases in open-access papers, as found by Europe PMC text mining. Sharing a sentence is not in itself a finding about the gene and the disease. The quoted sentences say what the papers report.
hepatocellular carcinoma (49 papers, 2015 to 2025). A malignant tumor that arises from hepatocytes. "HOXA13 and the lncRNA HOTTIP are coregulated in hepatocellular carcinoma, and the lncRNA HOXA11-AS has been implicated in regulating proliferation of several cancers, including gastric cancer." (PMID 38329124, 2024). "Additionally, two other studies showed the association between the elevated expression level of HOTTIP and each of dismal prognosis and metastasis in PC and hepatocellular carcinoma." (PMID 34069089, 2021). "Moreover, HOTTIP is reported to be associated with disease progression and predicts the outcome in hepatocellular carcinoma patients." (PMID 32307830, 2020). "Moreover, HOTTIP overexpression has been associated with worse outcome in several tumors, including hepatocellular carcinoma, tongue squamous cell carcinoma, colorectal cancer, osteosarcoma, breast cancer, gastric cancer, and even small-cell lung cancer." (PMID 30819158, 2019). "It is worth mentioning that HOTTIP has long been shown to be dysregulated in the early stages of hepatocellular carcinoma formation, and recent studies suggest a positive correlation between its expression and liver fibrosis progression." (PMID 34899344, 2021). "In previous studies, it has been verified that the knockdown of HOTTIP resulted in reduced cell proliferation and attenuated metastasis in hepatocellular carcinoma and in non-small cell lung cancer." (PMID 34069089, 2021). "The lncRNA HOTTIP plays key roles in multiple human cancers, including colorectal cancer, hepatocellular carcinoma, and gastric cancer." (PMID 32098245, 2020). "More recently, aberrant HOTTIP expression was reported in hepatocellular carcinoma and pancreatic cancer, among others." (PMID 32307830, 2020). "Aberrant expression of HOTTIP has been validated in various malignancies, including hepatocellular carcinoma, colorectal cancer, and gastric cancer." (PMID 31032351, 2019). "Previous study reported that knockdown of HOTTIP attenuated hepatocellular carcinoma cell proliferation in vitro and markedly abrogated tumorigenicity in vivo." (PMID 29884766, 2018). "MiR-192 and miR-204 were found to target HOTTIP in a sequence-specific and Ago2-dependent manner and inhibited proliferation of hepatocellular carcinoma." (PMID 28840253, 2018). "HOTTIP is also found to be associated with PRC2 and play a critical role in various malignancies including hepatocellular carcinoma, pancreatic cancer, gastric cancer, colorectal cancer and so on." (PMID 29041935, 2017). "lncRNA HOTTIP is a vital oncogenesis factor, significantly upregulated in hepatocellular carcinoma specimens." (PMID 28835257, 2017). "HOTTIP is upregulated in hepatocellular carcinoma, osteosarcoma, lung, prostate and other cancers; DLEU2 is deleted in lymphocytic leukemia and epigenetically silenced in myeloid leukemia." (PMID 28715488, 2017). "HOTTIP is upregulated in various carcinomas, such as lung carcinoma, gastric carcinoma (GC), pancreatic carcinoma, hepatocellular carcinoma (HCC) and squamous cell carcinoma." (PMID 28938659, 2017). "Increased HOTTIP expression has been reported in tongue squamous cell carcinoma, lung cancer, pancreatic cancer, hepatocellular carcinoma, osteosarcoma, gastric cancer, glioma and prostate cancer." (PMID 28036281, 2017). "LncRNAs such as HOTTIP in hepatocellular carcinoma and TUG1 in lung cancer interact with HOX development genes, namely HOXA13 and HOXB7, involved in numerous oncogenic processes, such as proliferation, motility and angiogenesis." (PMID 27340923, 2016). "Increased HOTTIP expression has been reported in lung cancer, pancreatic cancer, and hepatocellular carcinoma." (PMID 27806322, 2016). "Previous study reported that silencing HOTTIP attenuated hepatocellular carcinoma cell proliferation in vitro as well as tumorigenicity in vivo." (PMID 27806322, 2016).
hepatocellular carcinoma (continued). "So far, numerous lncRNA have been associated with poor prognosis in subsets of tumors, such as SCHLAP1 in prostate cancer, HOTTIP in hepatocellular carcinoma, gastric cancer and colon cancer, or FAL1 in ovarian cancer." (PMID 27340923, 2016). "Here, we for the first time demonstrated how microRNAs (miRNAs) impact onco-lncRNA HOTTIP expression and its biological significance in hepatocellular carcinoma (HCC)." (PMID 26710269, 2015). "HOTTIP primarily coordinates expression of genes associated the HOXA locus in fibroblasts, and a recent paper showed a close association between HOTTIP and HOXA13 in hepatocellular carcinomas (HCCs)." (PMID 25912306, 2015). "A few studies have discovered the relationship between aberrant HOTTIP expression and hepatocellular carcinoma." (PMID 26447755, 2015). "Similarly, other research indicated that specific lncRNA (HOTTIP and MALAT1) SNPs had the potential to be biomarkers in hepatocellular cancer (HCC) risk and prognosis." (PMID 36045445, 2022). "The posttranscriptional silencing of HOTTIP could significantly suppress viability of hepatocellular carcinoma cells." (PMID 28835257, 2017). "Interestingly, HOTTIP is significantly up-regulated in hepatocellular carcinoma (HCC) specimens compared with controls." (PMID 27733185, 2016). "Notably, the lncRNAs HOTTIP, H19, HOTAIR, MALAT1, antisense Igf2r (AIR), HOXA13, GTL2 (also called MEG3) and uc002mb have been reported in association with hepatocellular carcinoma (HCC)." (PMID 26172293, 2015). "Interestingly several studies investigating predicative biomarkers of cancer progression and patient outcomes in hepatocellular carcinoma have implicated the expression HOXA13 and HOTTIP as indicators of poor prognosis with high disease progression." (PMID 26633036, 2015). "We conclude that in hepatocellular carcinoma (HCC), HOTTIP influences glutaminolysis and sponges miR-205 to promote cell viability." (PMID 40616679, 2025). "The lncRNA HOTTIP (HOXA transcript at the distal tip), located near HOXA13, is implicated in the progression of hepatocellular carcinoma (HCC) and gastric cancer by regulating HOXA1345." (PMID 38322121, 2024). "HOTTIP is considered an oncogene as its overexpression has been observed in different cancers, such as hepatocellular carcinoma (HCC), pancreatic ductal adenocarcinoma, gastric cancer, and NPC." (PMID 39049088, 2024). "Interestingly, we detected one patient (P5) that not relapsed but the increase in the EV HOTTIP levels were linked to the diagnosis of Hepatocellular carcinoma 11 months after lung tumor resection." (PMID 34111710, 2021). "However, HOTTIP and HOXA13 have been associated with disease progression and worse outcome in hepatocellular carcinoma, with progression and gemcitabine resistance in pancreatic cancer, and with tumorogenesis and metastasis in esophageal squamous carcinoma and gastric cancer." (PMID 30819158, 2019). "Recently, two micro RNAs miR-192, miR-204 have been demonstrated to post-transcriptionally silence the HOTTIP lncRNA, leading to the reduced viability of hepatocellular carcinoma (HCC) cells, further validating a role for this lncRNA molecule." (PMID 28384324, 2017). "A study investigated the relationship between the lncRNAs HOTTIP, H19, and HOTAIR and miRNA 152, as well as the role of these interactions in the progression of HCV-induced liver lesions to hepatocellular carcinoma." (PMID 41465470, 2025). "HOXA13, a HOX gene, is most overexpressed in HCC and is known to be directly regulated by the lncRNA HOTTIP, and high expression of HOXA13 correlates with poorly differentiated hepatocellular carcinomas and increases sorafenib response in vitro models." (PMID 39682093, 2024). "In Hepatocellular carcinoma (HCC) patients, HOTTIP rs2071265 was related with an earlier recurrence." (PMID 33028884, 2020).
hepatocellular carcinoma (continued). "HOTTIP has been identified in human hepatocellular carcinoma (HCC) samples and is related to the disease outcomes and clinical progression of HCC patients; in addition, HOTTIP is dysregulated in the early stage of human HCC." (PMID 32098245, 2020). "Additionally, miR-125b was also identified as a posttranscriptional regulator of HOTTIP (HOXA distal transcript antisense RNA) in hepatocellular carcinoma (HCC)." (PMID 29147648, 2017). "HULC, MALAT-1, TUC338, TUC339, lncRNA-HEIH, MVIH, HOTAIR, lnc-RoR, and HOTTIP have all been associated with higher expression in hepatocellular carcinoma (HCC) compared with normal liver tissue, while MEG3 is repressed in HCC." (PMID 27007663, 2016). "Our results indicate that HOTTIP acts as a tumour suppressor in glioma, which is similar to its role in Hirschsprung (HSCR) disease, but different from its role in hepatocellular carcinoma (HCC)." (PMID 27733185, 2016). "In hepatocellular carcinoma (HCC), the expression of HOXA locus gene was co-regulated by HOTTIP and WDR5/ mixed lineage leukemia 1 (MLL1) complex." (PMID 27429196, 2016). "HOTTIP has been shown to promote cancer cell proliferation, invasion, epithelial-mesenchymal transition (EMT), and metastasis in several malignancies such as ovarian cancer, breast cancer, hepatocellular carcinoma and oral cancer 11-20." (PMID 40959107, 2025). "A recent study indicated that CMB9-22P13.1 could upregulate HOTTIP and activate HIF-1α/VEGF signaling, leading to enhanced hepatocellular carcinoma progression and angiogenesis." (PMID 36849926, 2023). "Also, HOTTIP promotes tumor growth and metastasis through regulating HOXA genes in hepatocellular carcinoma." (PMID 34983537, 2022). "It has been speculated that miRNA-192 and miRNA-204 directly suppress lncRNA HOTTIP and interrupt GLS1-mediated glutaminolysis in hepatocellular carcinoma." (PMID 33422015, 2021). "In tissue specimens, miR-192 and miR-204 expressions are low and HOTTIP is high in hepatocellular carcinoma compared with normal tissues, showing a negative correlation between these miRNAs and HOTTIP expression." (PMID 28840253, 2018). "Furthermore, HOTTIP has been identified as a negative prognostic factor in hepatocellular carcinoma patients." (PMID 29367594, 2018). "Furthermore, expression of HOTTIP has been identified as a negative prognostic factor in hepatocellular carcinoma patients." (PMID 29221115, 2017). "In addition, HOTTIP has been identified as a negative prognostic factor in hepatocellular carcinoma patients." (PMID 29041935, 2017). "Up-regulation of HOTTIP is a negative prognostic factor for hepatocellular carcinoma patients." (PMID 27144338, 2016). "Furthermore, expression of HOTTIP has been identified as a negative prognostic factor in hepatocellular carcinoma patients; however, the functional role of HOTTIP in cancer progression remains unknown." (PMID 25889214, 2015).
gastric cancer (48 papers, 2016 to 2025). A primary or metastatic malignant neoplasm involving the stomach. "Such EMT induction by HOTTIP has been linked to cisplatin resistance in gastric cancer, thus further validating HOTTIP mediated EMT in resistance against therapies." (PMID 35402278, 2022). "These SNPs variants were associated with corresponding HOTTIP expression, providing clues for further studies focused on HOTTIP SNPs and gastric cancer pathogenesis." (PMID 32725141, 2020). "In our study, we identified two SNPs (rs3807598 and rs2067087) in HOTTIP involved in gastric cancer susceptibility and the formation of mature HOTTIP." (PMID 32725141, 2020). "Here, we identified two functional SNPs associated with gastric cancer susceptibility that affect the expression of mature HOTTIP." (PMID 32725141, 2020). "Further studies are needed to investigate the association between HOTTIP SNPs and the prognosis of gastric cancer." (PMID 32725141, 2020). "Serum exosomal long noncoding RNA HOTTIP was significantly lower in 120 healthy controls than in 126 patients with GC p which suggested that HOTTIP is a novel potential diagnostic and prognostic biomarker test for gastric cancer." (PMID 35886934, 2022). "In addition, serum exosomal lncRNA HOTTIP was found to be a potential diagnostic index for gastric cancer patients." (PMID 36119470, 2022). "Interestingly, HOTTIP derived from circulating exosomes recently published by our group can be used as a potential diagnostic and prognostic biomarker of gastric cancer." (PMID 32246818, 2020). "Moreover, transfer of lncRNA HOTTIP increases resistance to platinum in gastric cancer cells, while increased serum HOTTIP lncRNA is associated with poor response to platinum." (PMID 33080788, 2020). "However, no investigation has focused on HOTTIP polymorphisms, which can affect HOTTIP expression in gastric cancer." (PMID 32725141, 2020). "With this in mind, we conducted the present study to identify functional SNPs in HOTTIP to determine any correlation of HOTTIP polymorphisms with gastric cancer susceptibility and prognosis, aiming to explore whether polymorphisms could affect the expression of mature HOTTIP." (PMID 32725141, 2020). "Exosomal HOTTIP expression was found to be higher in Gastric Cancer (GC) patients, with a significant correlation to the extent of invasion and TNM stage." (PMID 40703556, 2025). "Specifically, F. nucleatum has been shown to enhance exosome production in gastric cancer cells, which in turn increases HOTTIP expression and facilitates gastric cancer invasion via the miR-885-3p/EphB2/PI3K/AKT signaling pathway." (PMID 39948481, 2025). "These analyses showed 15 genes were implicated in the prognosis of gastric cancer, including AC011374.1, AC018781.1, ADAMTS9-AS1, AL139002.1, AL391152.1, HOTTIP, FLRT1, NKX2-1-AS1, ADAMTS9-AS2, LINC00326, VCAN-AS1, SERPINE1, POU6F2-AS2, IGF2-AS, and miR-145." (PMID 37696973, 2023). "HOTTIP functions as a sponge for miR-218, which has been found to have tumor suppressive functions in gastric cancer (GC)." (PMID 33920605, 2021). "It has been found that HOTTIP not only promotes the development of liver cancer, gastric cancer, lung cancer, tongue squamous cell carcinoma and other tumors, but also participates in the occurrence and development of OA." (PMID 33435956, 2021). "Considering this, COX analysis found that up‐regulated exosomal HOTTIP can be an independent prognostic factor in patients with gastric cancer." (PMID 32924276, 2020). "Previous studies have demonstrated that overexpression of lncRNA HOTTIP in gastric cancer promotes tumor invasion and results in poor prognosis." (PMID 32725141, 2020). "In gastric cancer, the lncRNA HOTTIP has been reported to promote IL-6 expression, inhibit T cell proliferation and promote immune escape in gastric cancer cells." (PMID 33173530, 2020). "The expression levels of exosomal HOTTIP in gastric cancer patients are higher than those in healthy individuals." (PMID 32924276, 2020).
gastric cancer (continued). "Among them, HOTTIP, transcribed from the 5′ tip of the HOXA cluster, is associated with various tumors including gastric cancer." (PMID 32725141, 2020). "In a study of 246 subjects including 126 gastric cancer patients and 120 healthy controls, serum exosomal lncRNA HOTTIP was identified as a potential biomarker for diagnosis and prognosis in gastric cancer." (PMID 31448238, 2019). "HOTTIP is a novel predictor of lymph node metastasis and survival in non-small cell lung cancer, gastric cancer and pancreatic cancer." (PMID 28108736, 2017). "Moreover, the knockdown of HOTTIP can inhibit the proliferation of gastric cancer cells, and patients with high HOTTIP expression have higher metastasis potential of rectal cancer cells." (PMID 39027044, 2024). "Several reports documented the modulation of HOTTIP expression in a variety of tumors, such as hepatocellular carcinomas, colorectal cancer, gastric cancer, pancreatic cancer as well as osteosarcoma and thereby of great value for diagnostic screening and therapeutic intervention." (PMID 37392284, 2023). "Correlation between lncRNA HOTTIP and clinicopathological parameters of gastric cancer (n = 106)." (PMID 32457911, 2020). "Recently, two studies have shown that HOTTIP is significantly overexpressed in gastric cancer cell lines and acts as a predictive factor for poor prognosis, suggesting that it may be a potential novel diagnostic and prognostic biomarker." (PMID 32725141, 2020). "This was consistent with another finding that up-regulation of exosomal HOTTIP in the serum of patients with gastric cancer might be of good predictive value for prognosis." (PMID 33585440, 2020). "However, the existence of HOTTIP in the circulating exosomes and the potential roles of exosomal HOTTIP in gastric cancer (GC) was poorly understood." (PMID 29486794, 2018). "We identified both IGFBP-3 and HOTTIP are the target genes of HoxA13 in gastric cancer." (PMID 27144338, 2016). "Furthermore, overexpression of HOTTIP was identified as an independent poor prognostic factor for patients with gastric cancer." (PMID 27835598, 2016). "HOTTIP, an exosomelncRNA, promotes its target HMGA1 in gastric cancer (GC) cells, causingEMT and cisplatin resistance." (PMID 38108852, 2024). "Several studies found that lncRNA HOTTIP may play a significant part in the initiation and progression of gastric cancer, and may be both a new prognostic marker and a prospective target for the therapy of gastric cancer." (PMID 37614816, 2023). "In gastric cancer (GC) cells, the exosomal lncRNA HOTTIP activates its target HMGA1, causing GC cells to undergo EMT and acquire cisplatin resistance." (PMID 35359397, 2022). "Previous studies have highlighted HOTTIP as a biomarker for NSCLC recurrence and as a prognostic biomarker for patients with gastric cancer." (PMID 38238652, 2024). "Some studies suggested that HOTTIP functions as an oncogene by regulating HOXA13 expression in esophageal squamous carcinoma and gastric cancer." (PMID 37392284, 2023). "The expression profile of HOTTIP and HOXA13 was documented as prognostic factor for a variety of cancers, such as pancreatic ductal adenocarcinoma and gastric cancer." (PMID 37392284, 2023). "Examples include the effect of HOTTIP on EMT in breast cancer, gastric cancer, osteosarcoma, ovarian cancer." (PMID 35402278, 2022). "It’s important that HOTTIP expression level was significantly correlated with the depth of invasion and TNM stage in gastric cancer." (PMID 36119470, 2022). "Exosomal HOTTIP regulates the expression of HMGA1 through binding to miR‐218, thereby promoting cisplatin resistance in gastric cancer." (PMID 32924276, 2020). "However, the role of HOTTIP polymorphism in gastric cancer has not been investigated." (PMID 32725141, 2020). "Conversely, silencing HOTTIP can reverse EMT and enhance the sensitivity of MDR gastric cancer cells to DDP, ADR, and 5-FU in vitro." (PMID 32460771, 2020).
gastric cancer (continued). "WDR5 has been shown to cooperate with HOTTIP to promote HOXA9 in prostate and pancreatic cancer and HOXA13 expression in esophageal and gastric cancer cells by increasing H3K4Me3 on their promoters." (PMID 29925347, 2018). "Similarly, HOTTIP was up-regulated in gastric cancer (GC) cell lines." (PMID 31533774, 2019).